RHPN2 (rhophilin Rho GTPase binding protein 2)
Description:
Binds specifically to GTP-Rho. May function in a Rho pathway to limit stress fiber formation and/or increase the turnover of F-actin structures in the absence of high levels of RhoA activity.
Synonyms: P76RBE; RHOBP
Tractability: Antibody: its Gene Ontology location is reachable by antibodies, with high confidence. PROTAC: ubiquitination databases record sites on it.
Gene: Protein-coding gene on chromosome 19 (32,978,592 to 33,064,888, reverse strand). Ensembl gene ENSG00000131941.
Subcellular location: Cytoplasm, perinuclear region
Pathways (Reactome):
Signal Transduction: RHO GTPases Activate Rhotekin and Rhophilins; RHOA GTPase cycle; RHOB GTPase cycle
Gene Ontology:
Molecular function: protein binding
Biological process: negative regulation of stress fiber assembly; signal transduction
Cellular component: plasma membrane; cytosol; perinuclear region of cytoplasm
Genetic constraint (gnomAD): Loss-of-function variants: 35 observed, 67.72 expected, observed/expected ratio (o/e) 0.52, 90% interval 0.39 to 0.69. The upper end of that interval is the gene's LOEUF score, 0.69, which puts it in group 2 of 6, group 1 being the genes least tolerant of losing a copy. Missense variants: 649 observed, 835.24 expected, observed/expected ratio (o/e) 0.78, 90% interval 0.73 to 0.83. Synonymous variants: 278 observed, 340.02 expected, observed/expected ratio (o/e) 0.82, 90% interval 0.74 to 0.9.
Homologues: Orthologues: chimpanzee RHPN2 (99% identical), macaque RHPN2 (98% identical), dog RHPN2 (90% identical), pig RHPN2 (88% identical), guinea pig RHPN2 (87% identical), mouse Rhpn2 (86% identical), rat Rhpn2 (85% identical), rabbit RHPN2 (84% identical), tropical clawed frog rhpn2 (62% identical), zebrafish rhpn2 (58% identical), Drosophila melanogaster Rhp (38% identical), Caenorhabditis elegans ego-2 (20% identical). Paralogues in human: RHPN1 (41% identical).
Diseases named in the same sentence as RHPN2 in open-access papers:
RHPN2 is named in the same sentence as 21 diseases in open-access papers, as found by Europe PMC text mining. Sharing a sentence is not in itself a finding about the gene and the disease. The quoted sentences say what the papers report.
prostate carcinoma (5 papers, 2019 to 2024). A carcinoma that arises from epithelial cells of the prostate gland. "In the present study, the microarray-based analysis implicated rhophilin Rho GTPase binding protein 2 (RHPN2) in prostate cancer." (PMID 31847864, 2019). "An analysis revealed that miR-205 inhibits the malignant progression of prostate cancer by suppressing its target gene rhophilin rho GTPase binding protein 2 (RHPN2)." (PMID 39595531, 2024). "For instance, miR-205 from hBMSC-derived exosomes slows prostate cancer progression by inhibiting RHPN2." (PMID 37248542, 2023). "In coherence with their findings, hBMMSC derived exosomal miR-205 inhibited prostate cancer cell proliferation, invasion, migration and induces apoptosis through the knockdown of RHPN2 mRNA." (PMID 35511336, 2022). "The upregulated miR-205 inhibited the proliferation, invasion, and migration of prostate cancer cells and promoted apoptosis by targeting RHPN2, and this was effected through miR-205-expressing exosomes derived from human bone marrow mesenchymal stem cells." (PMID 34335792, 2021). "This analysis showed that the RHPN2 gene had significantly elevated expression in prostate cancer samples and interacted with KLF6 gene, which was the core gene in gene interaction network." (PMID 31847864, 2019). "RHPN2 was a target of miR-205, and upregulated miR-205 inhibited prostate cancer cell proliferation, invasion, and migration and promoted apoptosis by targeting RHPN2." (PMID 31847864, 2019). "Initially, our initial results demonstrated that miR-205 was downregulated while RHPN2 was upregulated in prostate cancer cells." (PMID 31847864, 2019). "Microarray-based gene expression profiling of prostate cancer was adopted to identify differentially expressed genes and regulatory miRNAs, which identified the candidates RHPN2 and miR-205 as the study focus." (PMID 31847864, 2019). "The clonogenic assay subsequently showed that downregulated RHPN2 significantly repressed the colony-forming ability of prostate cancer cells (p < 0.05)." (PMID 31847864, 2019). "The Transwell assay displayed that silencing RHPN2 obviously suppressed prostate cancer cell invasion and migration (p < 0.05)." (PMID 31847864, 2019). "Through verifying RHPN2 expression in prostate cancer via the TCGA dataset, we found that RHPN2 expression was also upregulated in prostate cancer samples." (PMID 31847864, 2019). "miR-205 was downregulated, while RHPN2 was upregulated in prostate cancer cells." (PMID 31847864, 2019). "Collectively, our results suggest that exosome-mediated transfer of miR-205 from hBMSCs to prostate cancer cells suppresses proliferation, migration, and invasion of prostate cancer cells via downregulation of RHPN2, ultimately attenuating progression of prostate cancer." (PMID 31847864, 2019). "Moreover, in prostate cancer cells, RHPN2 mRNA and protein expression were reduced upon miR-205 mimic treatment, while miR-205 inhibition led to increased RHPN2 mRNA and protein expression." (PMID 31847864, 2019). "Additionally, the results of immunohistochemistry indicated that hBMSCs-derived miR-205 significantly decreased the RHPN2 level in prostate cancer tissues (p < 0.05)." (PMID 31847864, 2019). "In conclusion, hBMSCs-derived exosomal miR-205 could potentially be transferred to prostate cancer cells, thus inhibiting proliferation, invasion, and migration of prostate cancer cells, and promoting their apoptosis via suppression of RHPN2." (PMID 31847864, 2019). "The hBMSCs-derived exosomal miR-205 retards prostate cancer progression by inhibiting RHPN2, suggesting that miR-205 may present a predictor and potential therapeutic target for prostate cancer." (PMID 31847864, 2019). "Thus, RHPN2 knockdown suppressed proliferation, invasion, and migration, and promoted apoptosis of prostate cancer cells." (PMID 31847864, 2019).
prostate carcinoma (continued). "Therefore, in this study, we intend to explore the effects of hBMSCs-derived exosomal miR-205 on the progression of prostate cancer via regulating RHPN2 so as to provide novel potential therapeutic strategies for combating prostate cancer." (PMID 31847864, 2019). "Thus, we speculate that exosomal miR-205 might affect the progression of prostate cancer by regulating RHPN2." (PMID 31847864, 2019). "Furthermore, exogenous overexpression of RHPN2 could rescue miR-205-induced suppression of prostate cancer cell invasion and migration (p < 0.05)." (PMID 31847864, 2019). "In addition, it has been demonstrated that RHPN2 plays vital roles in multiple tumors, while there were no studies about the effects of RHPN2 on prostate cancer." (PMID 31847864, 2019).
lung adenocarcinoma (3 papers, 2015 to 2021). A carcinoma that arises from the lung and is characterized by the presence of malignant glandular epithelial cells. "Specifically, we found that higher levels of RHPN2 were associated with poor clinical outcome of patients with lung adenocarcinoma." (PMID 33552953, 2020). "Our previous work has demonstrated that RHPN2 was significantly either mutated or overexpressed in human lung adenocarcinomas." (PMID 33552953, 2020). "We have found that RHPN2 was significantly mutated in lung adenocarcinoma (LUAD)." (PMID 33552953, 2020). "Taken together, this study suggested that RHPN2 was involved in tumorigenesis of lung cancer via modulating c-Myc stability and the expression of its target GS in lung adenocarcinoma, which links RHPN2 and glutamine metabolism." (PMID 33552953, 2020). "Mutations in RHPN2 (5%), GLI3 (4%) and MRC2 (2%) have not been reported previously as driver genes in lung adenocarcinomas but were recurrently observed in our cohort and are nominated to be significantly mutated." (PMID 26647728, 2015).
malignant glioma (3 papers, 2015 to 2020). A grade III or grade IV glioma arising from the central nervous system. "Rhophilin Rho GTPase binding protein 2 (RHPN2) drives mesenchymal transformation of malignant gliomas and is likely to participate in actin skeleton organization." (PMID 33041669, 2020). "Furthermore, RHPN2 triggers the progression of malignant glioma via activation of RhoA, indicating that silencing of RHPN2 exerts an inhibitory impact on the development of malignancy." (PMID 31847864, 2019). "Of note, RHPN2 has been reported to be involved in the development of malignant glioma." (PMID 31847864, 2019). "A recent study further demonstrated that RHPN2 could drive mesenchymal transformation in malignant glioma via triggering RhoA activation." (PMID 26647728, 2015).
ovarian carcinoma (3 papers, 2022 to 2024). A malignant neoplasm originating from the surface ovarian epithelium. "RHPN2 (rhophilin Rho GTPase binding protein 2), encoding a member of the rhophilin family of Ras-homologous (Rho)-GTPase binding proteins, is frequently mutated in several cancer types, such as lung cancer, hepatocellular carcinoma, and ovarian cancer." (PMID 39548061, 2024). "RHPN2, a RhoA-binding protein, promotes malignant cell proliferation in ovarian cancer by activating the JAK2/STAT3 signaling pathway." (PMID 35893033, 2022). "Other reports have illustrated that RHPN2 activates the STAT3 pathway and expedites the progression of ovarian cancer, and the use of the STAT3 inhibitors signally eases the malignant cell behaviors induced by RHPN2." (PMID 35475457, 2022).
colorectal cancer (2 papers, 2015 to 2024). A primary or metastatic malignant neoplasm that affects the colon or rectum. "The present results suggest that the genetic variants of the CDKN1A (rs1321311) and RHPN2 (rs10411210) genes can be used as prognostic biomarkers for patients with surgically resected colorectal cancer." (PMID 25799222, 2015). "RHPN2, which was mutated in 13.64% and 30% of our rNEN-S and rNEN-L subjects, respectively, is required for the proliferation and invasion of multiple cancer cells and can be used as a prognostic biomarker for patients with surgically resected colorectal cancer." (PMID 39548061, 2024).
lung carcinoma (2 papers, 2020 to 2024). "Through CHX chase assay, we have found that RHPN2 stabilized c-Myc protein via phosphorylation of c-Myc at Ser62 in lung cancer." (PMID 33552953, 2020). "To investigate the effect of RHPN2 on the RhoA activity, we performed RhoA pull-down activation assay in RHPN2-expressing lung cancer cells." (PMID 33552953, 2020). "Since RHPN2 was required for the growth and invasion of lung cancer cells, we continued to determine the effect of RHPN2 on the growth of lung cancer in vitro and in vivo." (PMID 33552953, 2020). "To explore the biological function of RHPN2 in lung cancer, we generated lung cancer cells expressing low level of RHPN2 through lentivirus-mediated short hairpin RNA (shRNA)." (PMID 33552953, 2020). "Collectively, this work demonstrated the tumorigenic role of RHPN2 and identified the GS as a therapeutic target for a subset of lung cancer with a high level of RHPN2." (PMID 33552953, 2020). "CHX chase assay showed that RHPN2 remarkably retarded the degradation of c-Myc protein, which suggested that RHPN2 promoted the stability of c-Myc in lung cancer." (PMID 33552953, 2020). "Intriguingly, overexpression of RHPN2 conferred the resistance to glutamine depletion in lung cancer cells." (PMID 33552953, 2020). "We generated lung cancer cells expressing the FLAG-tagged RHPN2." (PMID 33552953, 2020). "Furthermore, lung cancer cells expressing high level of RHPN2 was resistance to glutamine depletion." (PMID 33552953, 2020). "Moreover, RHPN2 was also required for the growth and invasion of lung cancer cells in vitro and promoted tumorigenesis of lung cancer in vivo." (PMID 33552953, 2020). "RHPN2 was required for proliferation and invasion of lung cancer cells." (PMID 33552953, 2020). "However, the role of RHPN2 in lung cancer is not fully understood." (PMID 33552953, 2020). "Immunoblotting assay revealed that RHPN2 overexpression upregulated the levels of phosp-Myc at Ser62, which suggested that RHPN2 might regulate the stabilization of c-Myc via phosphorylation of c-Myc at Ser62 in lung cancer cells." (PMID 33552953, 2020). "To determine the potential upstream transcriptional factor mediated the RHPN2-induced upregulation of GLUL, we firstly examined the expression of GS and its potential transcriptional factors c-Myc, beta-catenin and YAP in a panel of lung cancer cell lines." (PMID 33552953, 2020). "As RHPN2 enhanced the growth of lung cancer in vivo, but not in vitro, we suspected that the growth environment specifically enhanced the proliferation of RHPN2-expressing lung cancer cells in vitro." (PMID 33552953, 2020). "Thus, we tested whether RHPN2 could affect RhoA activity and subsequently regulate Hippo-YAP pathway in lung cancer cells." (PMID 33552953, 2020).
glioma (1 paper, 2019). A benign or malignant brain and spinal cord tumor that arises from glial cells (astrocytes, oligodendrocytes, ependymal cells). "A previous study has confirmed that increased expression of RHPN2 in human glioma samples." (PMID 31847864, 2019).
goblet cell adenocarcinomas (1 paper, 2023). "However, in appendiceal cancers, mutations in the RHPN2 gene are rarely found in appendiceal goblet cell adenocarcinomas and appendiceal adenocarcinomas." (PMID 37509254, 2023).
lymph node metastases (1 paper, 2024). "The high-confidence driver genes RHPN2, MUC16, and MUC4 were significantly mutated in both small- and large-sized rNEN specimens, whereas mutations in MAN2A1, and BAG2 were only identified in large-sized specimens diagnosed with lymph node metastases." (PMID 39548061, 2024).
mastitis (1 paper, 2022). Inflammation of breast tissue during lactation or postpartum due to an obstructed duct or infection. "Other noteworthy genes (RHPN2, ACSS2, RHOU, and KRT7) showing lower expression in cows with mastitis have critical roles in biological pathways, cellular process, fatty acid synthesis, and metabolism." (PMID 35723402, 2022).
melanoma (1 paper, 2020). A malignant, usually aggressive tumor composed of atypical, neoplastic melanocytes. "For each of the genes, namely ZNFx1, RHPN2, STK11IP and UNC45A, from 1 to 3 siRNAs were designed and tested in melanoma cell line A375." (PMID 33041669, 2020). "Here we present the results of transient siRNA-mediated knockdown of the four of such genes, namely, UNC45A, STK11IP, RHPN2 and ZNFX1, in melanoma cell line A375, then assayed the cells for their viability, proliferation and ability to migrate in vitro." (PMID 33041669, 2020).
myopia (1 paper, 2024). "Eight pairs (protein-coding genes TOM1L2, MXRA7, RHPN2, and HINT1 for senile cataract, WARS1 and TDRD7 for AMD, STAT6 for myopia, and TPPP3 for DR) are newly reported in this study." (PMID 39408566, 2024).
ovarian endometriosis (1 paper, 2019). A non-neoplastic disorder characterized by the growth of endometrial tissue in the ovaries. "RHPN2 has been reported to be targeted by miR-182-5p, miR-363-3p, miR-200a-3p and miR-141-3p in ovarian endometriosis." (PMID 31847864, 2019).
cancer (11 papers, 2015 to 2025). A tumor composed of atypical neoplastic, often pleomorphic cells that invade other tissues. "Yet, despite increasing evidence that RHPN2 plays important roles in several aspects of tumorigenesis and cancer progression, it is still unclear whether the polymorphism itself alters the function of the protein expression." (PMID 25799222, 2015). "RHPN2, a member of rhophilin family of rho-binding proteins, regulates actin cytoskeleton and vesicular trafficking, and promotes mesenchymal transformation in cancer." (PMID 33552953, 2020). "Despite these reports, the mechanisms of the action of RHPN2 in cancer are not fully understood." (PMID 33552953, 2020). "To validate the RHPN2 expression in LUAD and other cancer types, we obtained the RNA sequencing data and corresponding clinical information from TCGA and found that RHPN2 mRNA levels were higher in tumor tissues than normal tissues in LUAD, LUSC and other cancer types." (PMID 33552953, 2020). "In all subtypes, four genes—PIK3CA, RHPN2, CRIPAK, and CDH1, were identified as cancer drivers (ZF10)." (PMID 37454130, 2023). "Some of them were previously demonstrated to play a role in other cancers (UNC45A, STK11IP), and some were not yet characterized (RHPN2 and ZNFX1)." (PMID 33041669, 2020).
tumor (5 papers, 2015 to 2020). "Work is ongoing to evaluate whether RHPN2 supports NB cell metastasis, and to examine the hypothesis that inhibition of tumor cell motility comprises a therapeutic approach in high-risk NB." (PMID 29259192, 2017). "We reanalyzed the RNA-seq data and found that RHPN2 was highly expressed in LUAD tumors (p<0.0001), with 44/59 (74.6%) patients having higher levels of RHPN2 mRNA in tumor tissues than the normal counterparts." (PMID 33552953, 2020). "Each of the three genes (RHPN2, MUC4 or ADAM21) that harbored mutations in more than one tumor has a regulatory role in cell adhesion and motility, cell functions essential to the metastatic process." (PMID 29259192, 2017). "Furthermore, both in vitro and in vivo experimental results in the present study revealed that miR-205 secreted from hBMSCs inhibited LNCaP cell proliferation, invasion, and migration, tumor growth, and promoted apoptosis by downregulating its target RHPN2." (PMID 31847864, 2019).
RHPN2 also shares sentences with these, for which no sentence is quoted: hepatocellular carcinoma (1 paper); infection (1); lymph node (1); mucinous adenocarcinoma of the appendix (1); neurological disease (1); senile cataract (1).